KRAS (KRas proto-oncogene, GTPase)
Diseases named in the same sentence as KRAS in open-access papers (continued):
Sharing a sentence is not in itself a finding about the gene and the disease.
tumor (continued). "Furthermore, the KRAS G12D tumor size distribution had a longer tail of large tumors, suggesting that its increased tumor number might be driven by more rapid growth than tumors driven by KRAS G12C." (PMID 37828026, 2023). "Consequently, patients with KRAS mutation may exhibit a reliance on MET signaling, specifically downstream of HGF, which is secreted by non-tumor cells and remains undetected under 2-D monolayer culture conditions." (PMID 37381723, 2023). "Thus, we counterstained the tumor cells for SOX9 after treatment with anti-KRAS antibodies." (PMID 37051535, 2023). "Therefore, HES1 likely functions as a migration-proliferation dichotomy node that controls tumor invasion and proliferation in KRAS mutant CRC, and its loss may be a predictor of tumor invasion and metastasis." (PMID 37749297, 2023). "We have shown in this study that, in a cohort of patients residing in the same region and whose tumor specimens were analyzed in the same laboratory, there is likely no racial difference in KRAS mutation frequency, but there is likely a significant racial difference in BRAF mutation frequency." (PMID 38139338, 2023). "Thus, in our study, the exclusion of oligometastatic patients and the presence of a higher proportion of poly-metastatic high tumor burden disease could have influenced the observed survival outcomes for KRAS p.G12C patients." (PMID 37509241, 2023). "Therefore, our results indicate that one of the main drivers of tumor resistance might be a direct consequence of the limited blockade of KRAS signaling by current inhibitors." (PMID 36928090, 2023). "Moreover, treatment of mice bearing KRAS WT tumors with the ferroptosis-selective inhibitor Liproxstatin-1 accelerated tumor onset to similar levels as FSP1 overexpression suggesting ferroptosis to be indeed responsible for suppression of tumor initiation capacity of WT cells in vivo." (PMID 36443441, 2023). "Factors involved in tumor-mediated NET formation include tumor-derived inflammatory and chemoattractant cytokines (IL-8, IL-6, TNF-α, G-CSF and IL-1β), tumor extracellular vesicles, tumor-activated platelets, tumor-derived HMGB1, KRAS oncogene mutation and hypoxia." (PMID 37511453, 2023). "Notably, DDR1 inhibition can attenuate KRAS-mutant tumour progression." (PMID 36864508, 2023). "Although SHP2 inhibitors offer a potential therapeutic solution for receptor tyrosine kinase-driven cancers, they may not adequately suppress tumor growth in KRAS-mutated cells when administered alone." (PMID 37662925, 2023). "The reasons why many KRAS G12C-mutated tumors may not respond initially to the inhibitors are not entirely clear, but tumor heterogeneity may play a significant role." (PMID 37894382, 2023). "Our research findings support this hypothesis, and we observed that the inhibition of pan-RAF and CSF1R using SJ-C1044, a highly potent competitive inhibitor, resulted in a significant delay in tumor growth in both cell-based and mouse models harboring mutant KRAS." (PMID 37504287, 2023). "Therefore, lactic acid may promote tumor angiogenesis by signaling through the EMT pathway or by activating KRAS, leading to tumor progression." (PMID 36776001, 2023). "Moreover, in transgenic mice, induction of KRAS-G12D protein expression using doxycycline resulted in tumor generation and promoted tumor growth, whereas cessation of induction of KRAS protein expression resulted in the shrinkage, or even clearing of the tumor." (PMID 37110848, 2023). "Tumours with BRAF-mutations might therefore direct early to a mesenchymal phenotype while tumours with KRAS-mutations might develop without EMT." (PMID 37344790, 2023).
tumor (continued). "However, of the 15 patients diagnosed with advanced local spread, 11 patients harboured KRAS mutations in the primary tumours, though this was not significant (p = 0.09)." (PMID 37761948, 2023). "Thus, we assessed whether anti-KRAS antibody can be internalized into live ex-vivo cultured mucosa-tumor pairs." (PMID 37051535, 2023). "However, comparisons of variant vs wild-type KRAS in the LO group showed no noticeable trend by tumor location from right (sHR, 0.97 [95% CI, 0.93-1.02]) to left (sHR, 1.15 [95% CI, 1.08-1.22]) and rectum (sHR, 1.10 [95% CI, 1.02-1.20])." (PMID 38032636, 2023). "No concordance between KRAS mutations in CTCs and primary tumours was found." (PMID 37761948, 2023). "There exist a close relationship between mutations of KRAS and MAPK1 and the resistance of NSCLC to EGFR-TKI targeted drugs such as Gefitinib and Erlotinib, which can cause sustained activation of the EGFR signaling pathway and accelerate tumor cell proliferation." (PMID 37065830, 2023). "Furthermore, in vivo ARL-17477 inhibited the tumor growth of KRAS-mutant cancer." (PMID 37402770, 2023). "Furthermore, the oncogenic contexts were qualitatively different from each other: loss of tumor suppressors generally led to increased rates of tumor initiation and growth in the KRAS backgrounds, had more muted effects in the BRAF context, and had variable effects in the EGFR context." (PMID 37828026, 2023). "However, while the shapes of the distributions at these two timepoints were quite well matched, KRAS G12D consistently produced ~2–4× greater tumor number than KRAS G12C, suggesting that KRAS G12D may also drive greater levels of tumor initiation." (PMID 37828026, 2023). "KRAS is the most common driver oncogene in CRC and many other tumors, based in large part on its ability to simultaneously activate BRAF, PI3K, and other signaling effectors, which collaborate to induce tumor proliferation, survival, and other processes associated with progression." (PMID 38001126, 2023). "For example, KRAS-mutation status has been linked to PPARδ-CCL2 expression (involved in M2 macrophage transformation and recruitment), reduced NK cell cytotoxicity by increased expression of HLA-E and PD-L1, and epithelial-mesenchymal transition (EMT), a sensitiser for tumours to NK cytotoxicity." (PMID 36864508, 2023). "The upregulation of SINGH_KRAS_DEPENDENCY_SIGNATURE was the only activated oncogenic signature in the LAD1 high-expression group, suggesting that the overexpression of LAD1 may facilitate the activation of K-Ras, resulting in the so-called “K-Ras addiction” of tumor cells." (PMID 36770773, 2023). "The overexpression or inhibition of regulators and effectors of KRAS and its downstream signalling pathways accelerates tumour progression, but fortunately, this process is influenced by multiple factors and often occurs at the early stages of tumour formation." (PMID 36835437, 2023). "However, even in the absence of tumor acquired KRAS mutations, patients with the KRAS-variant have a “KRAS-addicted” gene expression signature in their respective tumors, perhaps due to disruption of KRAS regulation by the miRNA let-7." (PMID 37728512, 2023). "Moreover, if small PDAC tumors do not release sufficient tumor cells and/or mutated DNA for KRAS, it is difficult to extrapolate and apply this method of diagnosis in the specific case of PDAC developed on CP tissue." (PMID 36765725, 2023). "Furthermore, we did not examine whether other AP-1 members showed expression correlation with CCL28 and KRAS, or whether they regulated tumour growth." (PMID 37380804, 2023).
tumor (continued). "KRAS vaccines may provide tumor specific treatments in PDAC." (PMID 37686543, 2023). "Nevertheless, the findings further support the idea that not all KRAS mutations are equal, and that a given point mutation may be associated with specific pathological effects in tumour cells’ signalling networks." (PMID 37627169, 2023). "A correlation between KRAS mutations and higher CEA and CA19-9 levels suggests that genetic alterations may have independent influences on CRC development, thus resulting in increased tumor biomarkers." (PMID 37311935, 2023). "Notably, the similar allele frequencies of the BRAF and KRAS mutations suggested their co-existence in the same cancer cells and not a clonal evolution of tumor cells exclusively with KRAS mutation." (PMID 36967525, 2023). "Moreover, conditioned medium (CM) from KRAS mutant, but not wild type, tumor cells increased the sensitivity of Day‐1 T‐cells to AICD, but this effect was significantly blocked when KRAS mutant tumor cells were pretreated with sodium dichloroacetate (DCA) to abolish lactic acid production." (PMID 36599679, 2023). "In our study, tumours without KRAS mutation showed higher SRHGLE values." (PMID 37509345, 2023). "Thus, it is possible that the location of the tumor, rather than the type of codon-specific KRAS mutation, plays a more significant role in this case." (PMID 37628934, 2023). "We also dissected the underlying molecular mechanisms and revealed that KRAS mutations could directly activate CD47 in cancer cells to inhibit the activity of macrophages, thereby leading to innate immune evasion and aggressive tumor progression." (PMID 36413402, 2023). "Furthermore, we noted increases in the expression levels of EGFR, P-ERK, GLUT1, P-mTOR, and P-4EBP in the N-WASPKOG12D mice, suggesting that the deletion of N-WASP in the keratinocytes enhanced KRas signaling and glucose uptake, resulting in aggressive tumor formation." (PMID 37760426, 2023). "However, the proportion of tumor cells, as defined by the orthogonally validated KRAS mutation for each case, did not vary much along with total depth and mean depth per cell per amplicon." (PMID 36765116, 2023). "Thus, to understand the biological correlations between 3D spheroid configurations and the tumor pathogenesis of MM in more detail, additional investigations with the objective of identifying additional unidentified factors related to KRAS and SOX2 will be our next projects." (PMID 36899895, 2023). "In addition, UCP2 silencing significantly reduced tumour size of KRAS-mutant PDAC xenografts." (PMID 36672360, 2023). "Furthermore, the concordance rate of KRAS mutation status between the primary CRC tumor and its corresponding metastases is high, supporting the notion that these mutations are acquired before the dissemination of the tumor cells to distant organs." (PMID 36899966, 2023). "However, the exact mechanism linking aberrant HES1 expression to KRAS/BRAF mutant tumor invasion and metastasis remains unknown." (PMID 37749297, 2023). "Furthermore, the KRAS gene is associated with a high tumor mutational burden, CD8+ tumor cell infiltration, and high programmed death ligand 1 expression, which may be associated with better efficacy of ICIs." (PMID 36915627, 2023).
tumor (continued). "A phase I clinical trial to determine the preliminary anti-tumor activity and safety in patients with advanced solid tumors and KRAS-G12C mutation showed that no significant clinical benefit was observed, with the best response to stable disease in four patients (40%)." (PMID 37662925, 2023). "However, sufficient and high-quality tumour tissue samples for KRAS detection may be difficult to obtain due to poor tolerance for invasive procedures and intratumoral heterogeneity." (PMID 38087207, 2023). "In addition to the change towards a pro-tumor phenotype, macrophages also incur a metabolic change, driven by NF-kB, which acts by increasing glycolysis, with a consequent increase in lactate production that enhances KRAS-driven tumor growth and contributes to the reduction in T-cells." (PMID 37298540, 2023). "While most PDAC cases are driven by canonical gain-of-function KRAS mutations, ConDoR reveals that the tumor analyzed here is driven by a truncal BRCA2 stop-gained mutation (p.Y600*), which likely inactivated the BRCA2 protein, a tumor suppressor essential for homologous recombination repair." (PMID 38037115, 2023). "Finally, based on its availability and solubility and after a preliminary study analyzing the effect on tumor cells’ viability, compound P14 was selected to biochemically study its interaction with KRAS, and to analyze putative effects on treated cancer cells’ signaling and viability." (PMID 36614192, 2023). "Additionally, to evaluate the effect of tumor suppression using TUS-007 in a subcutaneous xenograft model of SW620-luc human colon cells (homozygous KRAS G12V), tumor-bearing nude mice were administered TUS-007 (80 mg/kg), cetuximab (1 mg/body), or the vehicle control via intraperitoneal injection." (PMID 37513471, 2023). "Moreover, azaserine monotherapy demonstrated reduced tumor burden in KRAS/LKB1 co-mutant models." (PMID 37880766, 2023). "Thus, it would be interesting to investigate in future work whether the DGKζ/ERK3 axis plays differential roles in migration, invasiveness, and tumor progression of NSCLCs with different statuses of KRAS or EGFR." (PMID 37287450, 2023). "Increased KRAS-induced macropinocytosis in tumor cells may be a contributing mechanism." (PMID 37296864, 2023). "Our observations suggest that, although KRAS mutations may contribute to immunosuppressive properties, they do not fully predict tumor inflammation." (PMID 37558751, 2023). "Compared with that in normal tissues from Alb-Cre mice (liver-specific Cre recombinase line), the ubiquitination of KRAS at the site lysine 128 (K128) was increased nearly 4.4-fold in LC tumor tissues, suggesting that KRAS ubiquitination may be involved in Fbxl6-mediated hepatocarcinogenesis." (PMID 38124228, 2023). "Therefore, combinations with compounds that hit specific vulnerabilities of KRAS-driven cells may provide sufficient clinical efficacy for significant tumor treatment." (PMID 36048281, 2022). "Finally, we showed that the KRAS blocker deltarasin acts to downregulate IL1R1 (interleukin-1 receptor 1) expression in KRAS-mutant tumor cells and that the proposed KRAS/CCL2/IL1B signature is enriched in human cancers with high KRAS mutation frequencies, in which it portends a dismal prognosis." (PMID 35327394, 2022). "Considering that the G12C-specific inhibitor only targets the G12C amino acid change, we hypothesised that patients whose tumours harbour a co-occurring KRAS mutation may not respond well to this type of agents." (PMID 35177674, 2022).
tumor (continued). "Interestingly, in our population, the presence of KRAS mutation was not related with pathologic characteristics of the tumor: the T stage, presence of lymph node metastases, presence of perineural invasion and caudate lobe invasion." (PMID 36139531, 2022). "Furthermore, KRAS mutations were shown to upregulate GM-CSF expression in the TME, enhancing the infiltration of MDSCs which are known to be potent suppressors of effector T cell responses and therefore contribute to the evasion of anti-tumor immunity." (PMID 35965494, 2022). "In addition, since the upregulation of SLC7A5 is closely related to abnormal amino acid metabolism and immune evasion, in this study, we identified the regulatory mechanism of ZNF24 on SLC7A5, which is crucial for the blockade of tumor metabolism and immunotherapy of KRAS mutant LUAD." (PMID 36505791, 2022). "PAT8 presented p.G12D-mutated KRAS in primary tumor and wild-type KRAS in the liver metastasis; nevertheless, he presented neither a specific pattern nor a relevant cytotoxic activity against tumor target cells, with degranulation rates ranging from 5% to 10% for both NK and T cells." (PMID 35936004, 2022). "Tumor-related factors associated with an increased risks of recurrence or mortality in smokers include a T3 tumor, one to three affected lymph nodes, nonmetastatic diseases, a mutated KRAS status, and a wild-type BRAF status." (PMID 35207186, 2022). "Finally, there is a difference in the KRAS status of the primary tumor." (PMID 35312176, 2022). "In addition, the KRAS multi-site mutation rate was related to the presence or absence of mucus components and tumor size." (PMID 35837115, 2022). "In a retrospective analysis of over 4000 PDAC tumor samples, mutant KRAS was seen in 81% of PDAC and was associated with higher M1 macrophages and cancer-associated fibroblast infiltration and lower CD4+/CD8+, natural killer (NK) cells, MSI-H status, and TMB compared to KRAS wild-type samples." (PMID 36290818, 2022). "However, the identity of the KRAS-regulated cytokines appears to vary between tumor types." (PMID 35857848, 2022). "KRAS inhibition in consequence leads to an increased sensitivity of tumor cells to type I and II IFNs, which translates to higher expression of IFN-induced genes such as T cell chemoattractants and antigen presentation genes that could positively affect antitumor immunity in vivo." (PMID 35857848, 2022). "Since several inhibitors targeting KRAS oncoproteins carrying the G12C mutation have reached the clinic, our model raises a note of caution that high KSR expression levels may decrease tumour sensitivity to these as well as to forthcoming KRAS inhibitors." (PMID 35313064, 2022). "Collectively, these data indicate that 249C is efficacious in inhibiting tumor growth with minimal side effects in our investigations thus far, establishing in vivo proof-of-concept for targeting autophagy/MP/lysosomal acidification with 249C in mutant KRAS cancers." (PMID 35879364, 2022).